S100A4 (S100 calcium binding protein A4)
Diseases named in the same sentence as S100A4 in open-access papers (continued):
Sharing a sentence is not in itself a finding about the gene and the disease.
follicular adenomas (1 paper, 2015). "Our findings using the MS assay show the loss of S100A4 in follicular adenoma tissue compared with follicular thyroid carcinoma, so this difference in expression has diagnostic potential." (PMID 25880590, 2015). "S100A4 expression was greatly decreased in benign follicular adenomas compared with normal thyroid tissue." (PMID 25880590, 2015).
gallbladder cancer (1 paper, 2017). "In gallbladder cancer, loss of E-cadherin expression followed by an increase in S100A4 expression enhances tumor cell proliferation, motility, and invasion activity, which is mediated by the overexpression of c-myc and MMP-14." (PMID 29069865, 2017). "Gallbladder cancer patients with S100A4 overexpression is reported to exhibit a lower rate of survival than those without or low S100A4 expression." (PMID 29069865, 2017).
hemangioma (1 paper, 2015). A benign vascular lesion characterized by the formation of capillary-sized or cavernous vascular channels. "Also, others reported a high incidence of hemangiomas–benign tumors of vascular origin, in transgenic mice ubiquitously expressing S100A444, and S100A4-mediated endothelial cell motility might be another mechanism for the increased angiogenesis seen in these animals." (PMID 25677816, 2015).
Hyperammonemia (1 paper, 2023). An increased concentration of ammonia in the blood. "Shared DAP that were increased at both 6 and 24 h of hyperammonemia included Eif4b, Map4, Arpc1b, Eif3b, S100a4, Smad4, and Hist1h2bb." (PMID 37101412, 2023).
hyperreactivity (1 paper, 2023). "In this study, treatment with anti‐S100A4 antibody significantly inhibited Th2-mediated airway hyperreactivity and reduced the production of IL-4 and IL-13." (PMID 37873538, 2023).
hypopharyngeal cancer (1 paper, 2023). Carcinoma, predominantly squamous cell, arising from the epithelial cells of the hypopharynx. "In addition, we reviewed the literature and obtained several biomarkers that may be associated with the prognosis of hypopharyngeal cancer, such as PD-L1, SSR1, S100A4, PCDH20, and α2δ1." (PMID 36941989, 2023).
IgG4-related sclerosing disease (1 paper, 2009). "Our finding that loss of immune tolerance in myeloid S100A4+ DCs can mediate mAIP in mice may help to explain some pathogenic aspects of human AIP, an IgG4-related sclerosing disease." (PMID 19625278, 2009).
inflammatory bone disease (1 paper, 2017). "Extracellular S100A4 regulates bone formation in inflammatory bone disease, increasing the risk of fractures and delaying bone healing, and treating primary calvarial osteoblasts with recombinant S100A4 reduces matrix mineralization." (PMID 29204268, 2017).
intestinal tumors (1 paper, 2025). "Furthermore, intestinal tumors from the Vtnfl/fl S100a4‐Cre+ group exhibited lower creatine and ATP levels compared to those from the Vtnfl/fl S100a4‐Cre‐ group." (PMID 40538300, 2025).
kidney stones (1 paper, 2025). "We found that after kidney stone treatment, the expression of S100A4, ARPC1B, and CEBPD genes in diabetic mice was significantly elevated." (PMID 40718484, 2025).
leiomyoma (1 paper, 2023). A well-circumscribed benign smooth muscle neoplasm characterized by the presence of spindle cells with cigar-shaped nuclei, interlacing fascicles, and a whorled pattern. "Our data, demonstrating decreased expression of S100A4 and S100A1 particularly in mutated tumors and the increase in CACNA1D expression, suggest potential reduced binding of calcium and greater calcium entry into leiomyoma cells which could contribute to tumor calcification." (PMID 36835153, 2023).
meningioma (1 paper, 2021). A generally slow growing tumor attached to the dura mater. "Finally, S100A4 was one of the highly expressed genes in meningioma, a common primary tumor of the CNS that originates from the arachnoid." (PMID 33918416, 2021).
metastatic colon tumors (1 paper, 2012). "The very same research group also identified that niclosamide, which is an established antihelminthic drug, may act as a potential therapy against S100A4-mediated metastatic colon tumors." (PMID 23166536, 2012).
metastatic prostate carcinoma (1 paper, 2021). A carcinoma that arises from the prostate gland and has spread to other anatomic sites. "Collectively, these results suggest that bone-metastatic prostate cancer-derived S100A4 stimulates osteoclastogenesis." (PMID 33549040, 2021).
myelogenous leukemia (1 paper, 2015). "Protein S100-A4 belongs to a member of the S100 calcium-binding protein family, and it was observed to be up-regulated in doxorubicin-resistant myelogenous leukemia cells." (PMID 25628518, 2015). "In our present study, several calcium-binding proteins were identified in doxorubicin-resistant myelogenous leukemia cells, such as sorcin, protein S100-A4, annexin A4, calreticulin, etc., indicating that metal ions such as calcium might play a pivotal role in the development of chemoresistance." (PMID 25628518, 2015).
myositis (1 paper, 2014). "Increased serum levels of S100A4 were associated with several measures of disease activity in myositis patients overall." (PMID 25359220, 2014). "Circulating levels of S100A4 are elevated in patients with myositis and associate with several disease activity parameters, particularly with extramuscular components." (PMID 25359220, 2014). "Based on these findings we have conducted a study in order to determine the S100A4 serum levels in myositis patients, to evaluate the association between circulating S100A4 and myositis disease activity and to assess a potential role of S100A4 in cancer-associated myositis (CAM)." (PMID 25359220, 2014). "A weak inverse correlation between S100A4 levels and disease duration was observed in all myositis patients (r = −0.27; P = 0.006)." (PMID 25359220, 2014). "The aim was to evaluate S100A4 protein as a biomarker of disease activity and potential cancer development in patients with myositis." (PMID 25359220, 2014). "The levels of serum S100A4 were higher in all myositis patients than in healthy controls (31.5 (17.4 to 59.5) versus 23.8 (14.5 to 33.7) ng/ml, P <0.05)." (PMID 25359220, 2014). "All myositis patients had significantly higher serum levels of S100A4 protein compared to healthy controls (median (IQR): 31.5 (17.4 to 59.5) versus 23.8 (14.5 to 33.7) ng/ml, P <0.05)." (PMID 25359220, 2014). "Surprisingly, anti-TIF1-positive myositis patients (n = 17), who are more likely to develop cancer, had lower levels of S100A4 than anti-TIF1-negative ones (n = 87) (17.1 (11.3 to 25.1) versus 36.6 (21.8 to 66.7) ng/ml, P = 0.001)." (PMID 25359220, 2014). "In this study, we found increased S100A4 serum levels in all myositis patients and particularly in PM patients compared to those with DM and healthy individuals." (PMID 25359220, 2014). "Further studies evaluating the role of S100A4 in myositis are needed." (PMID 25359220, 2014). "Serum levels of S100A4 were compared between patients positive or negative for the myositis-specific and associated autoantibodies directed against Jo-1, Mi-2, PM-Scl and TIF1 antigens." (PMID 25359220, 2014). "In addition, we have previously demonstrated that S100A4 is expressed mainly by infiltrating mononuclear cells, few regenerating muscle fibres and endothelial cells in myositis." (PMID 25359220, 2014). "In summary, we have demonstrated that circulating S100A4 levels are elevated in myositis patients, especially in those with polymyositis, and correlate with several features of myositis disease activity, particularly with extramuscular involvement, but not with the presence of cancer." (PMID 25359220, 2014). "No relation between S100A4 levels and presence of cancer associated myositis was found." (PMID 25359220, 2014). "Thus, we suggest that S100A4 may either reflect diverse pathological processes that occur in different myositis subtypes and/or that it plays a more important role in PM than in DM." (PMID 25359220, 2014). "The levels of serum S100A4 were higher in healthy male compared to female subjects, but there were no significant sex-related differences in S100A4 levels in myositis patients." (PMID 25359220, 2014). "In addition, we have not observed any significant correlations between S100A4 serum levels and myositis disease activity or laboratory markers in patients with cancer-associated myositis (data not shown)." (PMID 25359220, 2014). "The levels of S100A4 were comparable between myositis with and without cancer." (PMID 25359220, 2014).
Nephropathy (1 paper, 2022). A nonspecific term referring to disease or damage of the kidneys. "In contrast, inhibition of S100A4 with niclosamide markedly attenuated fibronectin and α-SMA levels with FA nephropathy." (PMID 36078170, 2022).
oligoarticular JIA (1 paper, 2022). "S100A4, TIMP3, and NBL1 are overexpressed in pre-extension oligoarticular JIA FLS compared to polyarticular JIA FLS." (PMID 36167601, 2022).
orchitis (1 paper, 2025). Inflammation of one or both testes due to viral or bacterial infections. "In the UPEC-induced epididymo-orchitis model, we observed that S100a4-GFP+F4/80+ TMs were significantly increased in the testes and epididymis at day 7 after infection compared with the sham surgery control group." (PMID 41031892, 2025).
Osteopenia (1 paper, 2019). Osteopenia is a term to define bone density that is not normal but also not as low as osteoporosis. "The reduction of neither TMEM64 nor S100A4 discriminated well nonosteoporotic controls from osteopenia (area under the ROC curves, 0.6 and 0.55, respectively, not shown) or osteopenia and osteoporosis combined (area under the ROC curves, 0.646 and 0.627, respectively, not shown)." (PMID 31814858, 2019). "Neither TMEM64 nor S100A4 mRNAs discriminated well nonosteoporotic controls from osteopenia (area under the ROC curves, 0.614 and 0.543, respectively, not shown) or osteopenia and osteoporosis combined (area under the ROC curves, 0.667 and 0.618, respectively, not shown)." (PMID 31814858, 2019). "The levels of mRNAs of annexin A1, S100A4, and TMEM64 in human peripheral blood mononuclear cells were evaluated among 48 osteopenia and 23 osteoporosis patients compared to 17 nonosteoporotic controls." (PMID 31814858, 2019). "Thus, the aim of this study was to find out whether the levels of mRNAs for annexin A1, S100A4, and TMEM64 were significantly changed in the PBMCs of participants with osteopenia or with osteoporosis compared to nonosteoporotic controls." (PMID 31814858, 2019).
osteoporosis (1 paper, 2019). A condition of reduced bone mass, with decreased cortical thickness and a decrease in the number and size of the trabeculae of cancellous bone (but normal chemical composition), resulting in increased fracture incidence. "The reductions of S100A4 mRNA levels were found to be due to participants with other disorders, those receiving existing treatments for osteoporosis, males, and under 50-year olds." (PMID 31814858, 2019). "ROC analysis showed that the reduction in the level of mRNA for annexin A1, S100A4, or TMEM64 in the patients' peripheral blood mononuclear cells has a good diagnostic value for osteoporosis." (PMID 31814858, 2019). "This study is aimed at investigating the level of calcium-binding/associated proteins, annexin A1, S100A4, and TMEM64, in peripheral blood mononuclear cells associated with osteoporosis and its clinical significance." (PMID 31814858, 2019). "Three mRNAs, encoding calcium-binding/associated proteins, ANXA1, S100A4, and TMEM64, were found to be at a lower level in the PBMC preparations from osteoporosis patients than nonosteoporotic controls." (PMID 31814858, 2019). "The levels of mRNAs for annexin A1, S100A4, and TMEM64 were reduced in PBMCs from osteoporosis patients compared to nonosteoporotic controls; thus, the presence of these mRNAs marked the nonosteoporotic condition." (PMID 31814858, 2019).
ovarian clear cell cancer (1 paper, 2025). An invasive malignant neoplasm that arises from the ovary and is characterized by a predominance of clear and hobnail malignant epithelial cells. "Background/Objectives: S100A4, a small calcium-binding protein, promotes metastasis in a variety of human malignancies, but little is known about its involvement in ovarian clear cell carcinoma (OCCC)." (PMID 39857966, 2025).
ovarian serous carcinoma (1 paper, 2025). "Association of S100A4 and ALDH1A1 expression with clinical features of ovarian serous carcinoma." (PMID 40093000, 2025).
Parkinson disease (1 paper, 2018). A progressive degenerative disorder of the central nervous system characterized by loss of dopamine producing neurons in the substantia nigra and the presence of Lewy bodies in the substantia nigra and locus coeruleus. "Furthermore, peptides derived from neurotrophic sites of S100A4 protect neurons in cell models of Parkinson's disease and interact with/signal through ErbB." (PMID 30083275, 2018).
pituitary adenoma (1 paper, 2023). "SLC2A1, CLDN4, LAMC2, S100A4, and ITGB3 were significantly correlated with the invasiveness of pituitary adenoma (P<0.05)." (PMID 36936141, 2023).
pleural tuberculosis (1 paper, 2014). Inflammation of the pleura secondary to an infection with Mycobacterium tuberculosis. "Our study was designed to investigated the expression of S100A4 in pleural tuberculosis and analyze its relationship to the clinical course of pleural tuberculosis, aiming to explore the potential mechanism of pleural fibrosis caused by pleural tuberculosis." (PMID 24885536, 2014). "The expression of S100A4 in pleura was examined in 30 patients with pleural tuberculosis and 5 control (disease-free) patients by immunohistochemistry using the streptavidin-peroxidase (S-P) conjugated method." (PMID 24885536, 2014). "In the pleura of all 30 patients with pleural tuberculosis, S100A4 had a higher expression in the two- to eight-week duration of the disease." (PMID 24885536, 2014). "Our study found that S100A4 was significantly expressed in pleural tuberculosis, and was closely associated with the clinical course of pleural tuberculosis, while it did not express in normal pleural tissue." (PMID 24885536, 2014). "The expression of S100A4 in pleura was mainly distributed in the nucleus and cytoplasm of fibroblasts and vascular endothelial cells, and the positive rate was 90.0% (27 out of 30 patients with pleural tuberculosis)." (PMID 24885536, 2014). "So far, the role of S100A4 in the pathogenesis of pleural fibrosis resulting from pleural tuberculosis has not been reported." (PMID 24885536, 2014). "Our study found that S100A4 was positively expressed in pleural tuberculosis, mainly in the fibroblasts and not in normal pleural tissue." (PMID 24885536, 2014).
pulmonary tuberculosis (1 paper, 2023). A bacterial infection that affects the lungs and is caused by Mycobacterium tuberculosis. "In this study, transcriptome analysis of the peripheral blood of patients with pulmonary tuberculosis (PTB) revealed that S100A4 and GSDMD were significantly up-regulated in PTB patients’ peripheral blood." (PMID 37628889, 2023).
renal hypertension (1 paper, 2026). Hypertension caused by the kidney's hormonal response to narrowing or occlusion of the renal arteries. "Interestingly, the spatial transcriptomic analysis further reveals a unique population of S100A4+ vascular smooth muscle cells in camel rather than other mammalian kidneys, potentially involved in prevention of renal hypertension." (PMID 41632085, 2026).
retinal ischemia (1 paper, 2025). A ischemic disease that involves the retina. "Conversely, another study found that S100A4 overexpression exerts anti-apoptotic effects by upregulating the AKT signaling pathway in mice with retinal ischemia-reperfusion injury, highlighting the complex roles of S100A4 in different diseases." (PMID 40787447, 2025).
right ventricular dilation (1 paper, 2020). "Just as increased levels of troponin T are associated with right ventricular dilation, an increase in right ventricular pressure has been reported in mice overexpressing S100A4." (PMID 32218378, 2020).